HBEGF (heparin binding EGF like growth factor)
Description:
Growth factor that mediates its effects via EGFR, ERBB2 and ERBB4. Required for normal cardiac valve formation and normal heart function. Promotes smooth muscle cell proliferation. May be involved in macrophage-mediated cellular proliferation. It is mitogenic for fibroblasts, but not endothelial cells. It is able to bind EGF receptor/EGFR with higher affinity than EGF itself and is a far more potent mitogen for smooth muscle cells than EGF. Also acts as a diphtheria toxin receptor.
Synonyms: DTR; DTS; HEGFL; DTSF
Tractability: Antibody: a drug acting on it is in phase 1 trials; its Gene Ontology location is reachable by antibodies, with high confidence; UniProt places it where antibodies can reach, with medium confidence; UniProt predicts a signal peptide or a membrane-spanning region.
Target class: Secreted protein
Gene: Protein-coding gene on chromosome 5 (140,332,843 to 140,346,614, reverse strand). Ensembl gene ENSG00000113070.
Subcellular location: Secreted, extracellular space (Heparin-binding EGF-like growth factor); Cell membrane (Proheparin-binding EGF-like growth factor)
Subcellular location (Human Protein Atlas): Golgi apparatus; Vesicles; Predicted to be secreted
Pathways (Reactome):
Signal Transduction: Downregulation of ERBB2 signaling; EGFR Transactivation by Gastrin; EGFR downregulation; EGFR interacts with phospholipase C-gamma; ERBB2 Activates PTK6 Signaling; ERBB2 Regulates Cell Motility; Estrogen-dependent nuclear events downstream of ESR-membrane signaling; Extra-nuclear estrogen signaling; GAB1 signalosome; GRB2 events in EGFR signaling; GRB2 events in ERBB2 signaling; Nuclear signaling by ERBB4; PI3K events in ERBB2 signaling; PI3K events in ERBB4 signaling; PI5P, PP2A and IER3 Regulate PI3K/AKT Signaling; PIP3 activates AKT signaling; PTK6 promotes HIF1A stabilization; RAF/MAP kinase cascade; SHC1 events in EGFR signaling; SHC1 events in ERBB2 signaling; SHC1 events in ERBB4 signaling; Signaling by EGFR; Signaling by ERBB2; Signaling by ERBB4
Disease: Constitutive Signaling by Aberrant PI3K in Cancer; Inhibition of Signaling by Overexpressed EGFR; Signaling by ERBB2 KD Mutants; Signaling by ERBB2 TMD/JMD mutants; Uptake and function of diphtheria toxin
Vesicle-mediated transport: Cargo recognition for clathrin-mediated endocytosis; Clathrin-mediated endocytosis
Gene Ontology:
Molecular function: growth factor activity; heparin binding; protein binding; receptor ligand activity; transmembrane receptor protein tyrosine kinase activator activity; epidermal growth factor receptor binding
Biological process: cell chemotaxis; epidermal growth factor receptor signaling pathway; positive regulation of cell migration; positive regulation of phosphatidylinositol 3-kinase/protein kinase B signal transduction; positive regulation of wound healing; muscle organ development; positive regulation of cell population proliferation; signal transduction; cell migration; ERBB2-EGFR signaling pathway; ERBB2-ERBB4 signaling pathway; negative regulation of glycoprotein biosynthetic process; positive regulation of cell growth; positive regulation of keratinocyte migration; positive regulation of smooth muscle cell proliferation; wound healing, spreading of epidermal cells
Cellular component: cell surface; extracellular region; clathrin-coated endocytic vesicle membrane; endocytic vesicle membrane; plasma membrane
Genetic constraint (gnomAD): Loss-of-function variants: 7 observed, 17.84 expected, observed/expected ratio (o/e) 0.39, 90% interval 0.22 to 0.74. The upper end of that interval is the gene's LOEUF score, 0.74, which puts it in group 3 of 6, group 1 being the genes least tolerant of losing a copy. Missense variants: 181 observed, 240.97 expected, observed/expected ratio (o/e) 0.75, 90% interval 0.67 to 0.85. Synonymous variants: 88 observed, 102.2 expected, observed/expected ratio (o/e) 0.86, 90% interval 0.72 to 1.03.
Homologues: Orthologues: chimpanzee HBEGF (99% identical), pig HBEGF (91% identical), rabbit HBEGF (89% identical), dog HBEGF (89% identical), guinea pig HBEGF (85% identical), macaque HBEGF (82% identical), rat Hbegf (82% identical), mouse Hbegf (81% identical), zebrafish hbegfa (44% identical), tropical clawed frog hbegf (41% identical), zebrafish hbegfb (41% identical). Paralogues in human: AREG (26% identical), EPGN (16% identical), BTC (15% identical), TGFA (15% identical), EREG (12% identical).
Diseases named in the same sentence as HBEGF in open-access papers:
HBEGF is named in the same sentence as 217 diseases in open-access papers, as found by Europe PMC text mining. Sharing a sentence is not in itself a finding about the gene and the disease. The quoted sentences say what the papers report.
breast carcinoma (55 papers, 2011 to 2025). "Of these, HBEGF is abundantly expressed in human adipose tissue, TGFα has been implicated in the development of obesity-related postmenopausal breast cancer using rodent models, and EGF has received much attention as a therapeutic target in anticancer therapies." (PMID 27525640, 2017). "In preclinical models, the association between EGFR pathway activation and breast cancer brain metastases, including through EGFR ligand heparin binding EGF (HBEGF) overexpression, was also reported." (PMID 36980614, 2023). "In this study, we provide evidence which suggests that BHLHE40 is a pro-metastasis factor in breast cancer cells which promotes tumor cell survival and migration by modulating exosomic secretion of heparin-binding epidermal growth factor (HBEGF)." (PMID 30285805, 2018). "For example, MMP-2 processing growth factors, including heparin-binding EGF-like growth factor (HB-EGF), in response to gonadotrophin-releasing hormone (GnRH) activation can promote cell proliferation, with HB-EGF activity linked to breast cancer growth." (PMID 29874869, 2018). "To further validate our cell line as a new model for breast cancer studies, we selected HBEGF and AREG genes known to play important role in breast tumorigenesis and proposed as therapeutic targets for various human cancers including breast cancer." (PMID 23029355, 2012). "We also noticed HBEGF protein, which was reported to be involved in breast cancer cell metastasis." (PMID 37468844, 2023). "The study, which included 311 early-stage breast cancer patients, investigated associations between preoperative serum levels of EGFR and EGFR ligands (epidermal growth factor, heparin-binding epidermal growth factor (HBEGF), amphiregulin, transforming growth factor-α and betacellulin) and survival." (PMID 33024132, 2020). "HBEGF is a potent mitogen for keratinocytes, hepatocytes, smooth muscle cells and fibroblasts, and its expression is elevated in human cancers, including hepatocellular and gastric carcinoma, breast carcinoma, melanoma, colon cancer, pancreatic cancer, glioma and glioblastoma." (PMID 26011628, 2015). "HBEGF, a ligand for EGFR, has been specifically identified in brain metastasis and demonstrated to enhance invasion in breast cancer cells." (PMID 38714954, 2024). "The seventh cited paper was the only basic study in the 10 most cited papers, which anchored COX2, HBEGF, and ST6GALNAC5 as the key genes mediating breast cancer brain metastasis." (PMID 37091185, 2023). "In mammary tumors, for example, TAMs secrete epidermal growth factor receptor (EGFR) family ligands, including heparin-binding EGF-like growth factor (HB-EGF), and activate STAT3-related signaling pathways to fuel tumor cell proliferation." (PMID 34178692, 2021). "Three genes, Cox2, HBEGF and ST6GALNAC5, identified by Bos and colleagues, were shown to promote transendothelial migration in breast cancer cell lines." (PMID 29784888, 2018). "A recent study has shown that breast cancer cell products can induce OSM from both monocytes and macrophages and that OSM cooperated with heparin-binding EGF-like growth factor (HB-EGF) to modulate tumour cell chemotaxis." (PMID 24381786, 2013). "Collectively, our data underscore the pivotal role of P4 and EGF signaling cross-talk as well as the impact of PRA/PRB ratio for controlling key target genes such as HBEGF and AREG involved in breast cancer development and metastasis." (PMID 23029355, 2012). "We previously reported that PR SUMOylation is transcriptionally repressive at a limited number of endogenous gene loci, including HBEGF, IRS1, and STC1; all three gene products are known to contribute to breast cancer cell proliferation." (PMID 22697792, 2012). "Taken together, these findings suggest that the three hubs, NEBL, HBEGF, and PAPD7, in the differential networks play important roles in growth and development of breast cancer cells, and may thus become potential novel therapeutic targets." (PMID 25057922, 2014).
breast carcinoma (continued). "Interestingly, HBEGF, together with two other genes, COX2 and ST6GALNAC5, mediate breast cancer cell passage through the blood-brain barrier." (PMID 24403051, 2014).
ovarian carcinoma (27 papers, 2005 to 2025). A malignant neoplasm originating from the surface ovarian epithelium. "qRT-PCR demonstrated that HBEGF expression in PBMCs from ovarian cancer patients was 9-fold higher than in healthy donors, and flow cytometry confirmed that the monocyte population was positive for HB-EGF." (PMID 27888810, 2016). "Previous studies have demonstrated that the native ligand of epidermal growth factor receptor (EGFR) and ErbB4, heparin-binding EGF-like growth factor (HB-EGF), plays a critical role in the progression of ovarian cancer and is associated with prognosis of ovarian cancer." (PMID 30937184, 2019). "The EGFR‐COPA/GRN/HBEGF pairs were expressed at higher levels in the metastatic tumors than those in the primary tumors, suggesting that these cell‐to‐cell connections might be important for ovarian cancer metastasis." (PMID 34459128, 2021). "The aim of this study is to investigate whether the ADAM17 substrates Nectin-4, Heparin-binding EGF-like growth factor (HB-EGF) and Amphiregulin (AREG) could function as potential tumor markers for ovarian cancer." (PMID 36497350, 2022). "Monocytes are the primary immune cell in PBMCs that secrete HB-EGF; therefore, we compared expression of HBEGF in PBMCs of healthy donors and ovarian cancer patients to determine if HB-EGF may play a role in ovarian cancer." (PMID 27888810, 2016). "For example, heparin-binding EGF-like growth factor (HB-EGF), neuregulin-1 beta (NRG1β), insulin-like growth factor 1 (IGF1), and hepatocyte growth factor (HGF) are all expressed in tumors and found at higher levels in ascites fluid of ovarian cancer patients compared to healthy controls." (PMID 26648788, 2015).
gastric cancer (20 papers, 2009 to 2025). A primary or metastatic malignant neoplasm involving the stomach. "The increased expression of EGFR ligands, including transforming growth factor TGF-α, heparin-binding EGF-like growth factor (HB-EGF), and amphiregulin, is associated with clinical prognosis in many cancers such as gastric cancer." (PMID 22646534, 2012). "Therefore, NCAPD3 knockdown may activate IRF7, DDIT3, and HBEGF expression to promote gastric cancer cell apoptosis." (PMID 38711992, 2024). "IL1B promotes the shedding of heparin-binding EGF-like growth factor (HB-EGF), an EGFR ligand, in gastric cancer cells." (PMID 23115635, 2012).
glioblastoma (20 papers, 2005 to 2026). The most malignant astrocytic tumor (WHO grade IV). "When filtering data to the most aggressive type of brain tumors, IDHWT mesenchymal‐like glioblastomas, HBEGF upregulation is associated to halved survival time (N = 53, p = 0.0182)." (PMID 41181988, 2026). "HBEGF is upregulated in mesenchymal‐like glioblastoma, especially when compared to lower grade astrocytomas or glioblastomas from classical/astrocytic groups." (PMID 41181988, 2026). "Interestingly, we found that DSE selectively regulated heparin-binding EGF-like growth factor (HB-EGF)-induced signaling in glioblastoma cells." (PMID 29864158, 2018). "HBEGF is a ligand for the EGFR, one of the most commonly amplified receptor tyrosine kinases in glioblastoma, which may be a clinically relevant target." (PMID 33828969, 2021). "HBEGF is a confirmed target for Hsa-miR-11181-5p.However, RT-qPCR results indicated no significant transcript level changes inHBEGF in glioblastoma tumours compared to meningioma tissues." (PMID 34455717, 2021).
glioma (12 papers, 2013 to 2026). A benign or malignant brain and spinal cord tumor that arises from glial cells (astrocytes, oligodendrocytes, ependymal cells). "HBEGF and TGFA serve as established ligands for EGFR, and their intricate interplay triggers a cascade of signaling pathways implicated in glioma development." (PMID 39722126, 2024). "Consistently, lower expression levels of AKT2and TGFBR1 were detected in higher grade gliomas compared to other types of brain tumours, which was inverse tothe level of expression detected for the heparin-binding EGF-like growth factor (HBEGF) gene." (PMID 34455717, 2021). "Given that there are drugs which target HBEGF, glioma and HBEGF may make for an interesting target-indication pair for future studies." (PMID 39565278, 2025). "Our study identified HBEGF, a potent mitogen expressed on plasma membrane and key regulator of EGFR signaling, as an accessible target and an important player driving glioma phenotypic plasticity." (PMID 41181988, 2026). "Myeloid/microglial cells can communicate with MAN1C1-expressing glioma cells via signals produced (SPP1, GRN, PSAP, HBEGF, LGALS9, WNT5A)." (PMID 39333557, 2024). "In glioma cells, it has been shown that HGF stimulates the transcription of EGFR ligands such as transforming growth factor α (TGF α) and heparin-binding EGF-like growth factor (HB-EGF), whose inhibitions result in the failure of EGFR activation involving Y845 phosphorylation." (PMID 23702846, 2013). "Additionally, we identified five genes that not been implicated in glioma previously: CEP192 (18p11.21), D2HGDH (2q37.3) FAIM (3q22.3), HBEGF (5q13.3) and SLC8A1 (2p22.1)." (PMID 39565278, 2025). "We searched for differential gene expression of HBEGF and D2HGDH in non-tumour and glioma samples from the Rembrandt and TCGA studies, using the GlioVis tool." (PMID 39565278, 2025).
cardiac hypertrophy (11 papers, 2012 to 2024). "For example, ADAM12 was shown to act as a sheddase for heparin-binding EGF-like growth factor (HB-EGF) during cardiac hypertrophy and under hypoxia in head and neck, lung, and pancreatic cancer cells, leading to the formation of invadopodia and increasing cancer cell invasion." (PMID 28148288, 2017).
colon carcinoma (11 papers, 2010 to 2024). "We also identified 3 cancer-associated genes, GAN13, HBEGF, and PPP2R3A, with significantly decreasing expression levels in colon cancer (Group II)." (PMID 24564330, 2013). "As a possible mechanism of chemotherapy resistance in CRC, the authors proposed that shed SDC1 may interact with soluble heparin-binding EGF-like growth factor enhancing the activation of EGFR and downstream signaling, which in turn decreases the chemotherapeutical sensitivity of colon cancer cells." (PMID 36353562, 2022).
asthma (10 papers, 2014 to 2024). "However, based on our data, we can speculate that it is repetitive exposure, rather than enhanced responsiveness, to S1P that determines increased expression of pro-remodelling factors observed in asthma, that is HBEGF, RGS4 and PLAUR." (PMID 25041788, 2014).
lung carcinoma (10 papers, 2015 to 2025). "HBEGF has been shown to be upregulated in several cancers, including lung cancer." (PMID 37324026, 2023). "The expression of HBEGF and its role in lung cancer have been studied by several scientists." (PMID 37324026, 2023). "Taken together, these data implied that PM induces an increase in HBEGF expression in mouse lungs, which may in turn increase lung cancer metastasis." (PMID 36352257, 2022). "Furthermore, in human lung cancers, HBEGF expression has been positively correlated with levels of EGFR, regardless of EGFR mutational status." (PMID 34494649, 2021). "Since heparin-binding EGF-like growth factor (HB-EGF) was reported to be a promising therapeutic target for lung cancer, we investigated the role and mechanism of HB-EGF during arsenic-induced carcinogenesis and development of lung cancer." (PMID 32695675, 2020). "E xpression of the hub genes HBEGF, GJA4, DDR1, CD24, TBX2, GATA3, and SASH1 did not appear to be prognostic in lung cancer." (PMID 37324026, 2023).
lung fibrosis (10 papers, 2018 to 2025). "Enrichment analysis of the DEGs and protein–protein interaction analysis using String database demonstrated an association of HBEGF and NAMPT together with proteins involved in inflammatory and lung fibrosis pathways." (PMID 36388923, 2022). "Severe acute respiratory syndrome coronavirus (SARS-CoV) infection leads to the upregulation of EGFR ligands such as heparin-binding EGF-like growth factor (HB-EGF) and amphiregulin (AREG), and overactivation of EGFR leads to severe lung damage and pulmonary fibrosis." (PMID 34517756, 2021).
liver fibrosis (9 papers, 2015 to 2022). "While heparin-binding EGF-like growth factor (HB-EGF) was identified to suppress fibrosis (see also below), amphiregulin (AR) was shown to promote liver fibrosis via direct induction of HSC activation and proliferation." (PMID 31601007, 2019).
Obesity (9 papers, 2014 to 2024). Accumulation of substantial excess body fat. "Second, five proteins (CCL25, GRIA4, HBEGF, NPPA and RETN) were also considered because they have been reported to be associated with obesity." (PMID 35879730, 2022). "In addition, the proteins CCL25, GRIA4, HBEGF, NPPA and RETN, which are affected by RNAm-SNPs, have been reported to be related to obesity." (PMID 35879730, 2022).
pancreatic cancer (9 papers, 2005 to 2024). "In pancreatic cancer cell lines, GPC1 plays a key role in the mitogenic stimuli provided by fibroblast growth factor 2 (FGF2) and heparin-binding EGF-like growth factor (HB-EGF)." (PMID 36142190, 2022).
breast tumors (8 papers, 2014 to 2022). "The clinical relevance of our findings is evidenced by the fact that the elevated expression of BHLHE40 and HBEGF in breast tumors is associated with poor prognosis of patients with TNBC and chemoresistance." (PMID 30285805, 2018). "Among the cytokines and growth factors affected by BHLHE40-KD in LM cells, the expression level of HBEGF mRNA is positively correlated with the expression level of BHLHE40 mRNA in all four major subtypes of breast tumors in the TCGA database." (PMID 30285805, 2018). "In the present work, we will analyse the expression of three genes of interest (PTGS2, HBEGF, and ST6GALNAC5) in the FFPE tissue of primary TN phenotype breast tumours with CNS metastasis compared to patients who do not present with cerebral metastasis." (PMID 27170832, 2016).
colorectal cancer (8 papers, 2012 to 2024). A primary or metastatic malignant neoplasm that affects the colon or rectum. "HNSCC and colorectal cancer cell lines with acquired cetuximab resistance showed, amongst others, upregulated HBEGF gene expression." (PMID 35264144, 2022). "Among the five ligands that were found only in MC tissues, bone morphogenetic protein 4 (BMP4), hyaluronic acid synthase 2 (HAS2), and heparin-binding epidermal growth factor-like growth factor (HBEGF) were reported to be involved in cell proliferation or cell migration in colorectal cancer." (PMID 37091868, 2023).